NBEAP1 (neurobeachin pseudogene 1)
Synonyms: BCL8A; formerly BCL8
Gene: Transcribed unprocessed pseudogene on chromosome 15 (20,657,638 to 20,688,408, reverse strand). Ensembl gene ENSG00000258590.
Diseases named in the same sentence as NBEAP1 in open-access papers:
NBEAP1 is named in the same sentence as 10 diseases in open-access papers, as found by Europe PMC text mining. Sharing a sentence is not in itself a finding about the gene and the disease. The quoted sentences say what the papers report.
cystic lymphangioma (1 paper, 2021). "Instead, a mosaic 15q11.1-q11.2 deletion encompassing NBEAP1 and POTEB has been suggested to serve as a factor underlying pathogenesis of diffuse lymphangiomatosis with several typical symptoms, including large cystic lymphangioma over the left abdomen, thigh and vulva." (PMID 33435586, 2021).
fucosidosis (1 paper, 2021). "Also, the 15q11.1-q11.2 microdeletion encompassing several genes, including two OMIM genes, namely NBEAP1 (OMIM # 601889) and POTEB (OMIM # 608912), has not been linked, so far, to fucosidosis." (PMID 33435586, 2021).
Prader-Willi syndrome (1 paper, 2019). "The deletion detected at 15q11.1-q11.2 with the aCGH showed that 106 genes are contained in this deletion including several OMIM genes, as well as NBEAP1, responsible for B cell leukemia in translocation events, and NDN, belonging to the contiguous genes responsible for the Prader Willi syndrome." (PMID 31474980, 2019).
NBEAP1 also shares sentences with these, for which no sentence is quoted: lymphoma (3 papers); anaplastic large cell lymphoma (1); B cell CLL (1); B-cell lymphoma (1); Burkitt lymphoma (1); diffuse lymphangiomatosis (1); MALT lymphoma (1).